ARHGEF12 (Rho guanine nucleotide exchange factor 12)
Description:
Acts as guanine nucleotide exchange factor (GEF) for RhoA GTPase and may act as GTPase-activating protein (GAP) for GNA12 and GNA13. May play a role in the regulation of RhoA GTPase by guanine nucleotide-binding alpha-12 (GNA12) and alpha-13 (GNA13). Promotes endothelial cell and actin stress fiber reorientation in response to mechanotransduction (By similarity).
Synonyms: KIAA0382; LARG; PRO2792
Tractability: Antibody: the Human Protein Atlas places it where antibodies can reach. PROTAC: ubiquitination databases record sites on it; its protein half-life has been measured; a small molecule that binds it is known.
Target class: Enzyme; Hydrolase
Gene: Protein-coding gene on chromosome 11 (120,336,238 to 120,489,937, forward strand). Ensembl gene ENSG00000196914.
Subcellular location: Cytoplasm; Membrane
Subcellular location (Human Protein Atlas): Cytosol; Plasma membrane; Nucleoplasm
Pathways (Reactome):
Signal Transduction: CDC42 GTPase cycle; G alpha (12/13) signalling events; NRAGE signals death through JNK; RHOA GTPase cycle; RHOB GTPase cycle; RHOC GTPase cycle
Developmental Biology: Sema4D induced cell migration and growth-cone collapse
Gene Ontology:
Molecular function: G protein-coupled receptor binding; guanyl-nucleotide exchange factor activity; protein binding; GTPase activator activity
Biological process: G protein-coupled receptor signaling pathway; Rho-activating G protein-coupled receptor signaling pathway; actin filament organization; regulation of small GTPase mediated signal transduction; Rho protein signal transduction; intracellular signal transduction
Cellular component: cytoplasm; extracellular exosome; cytosol; membrane
Genetic constraint (gnomAD): Loss-of-function variants: 52 observed, 177.64 expected, observed/expected ratio (o/e) 0.29, 90% interval 0.23 to 0.37. The upper end of that interval is the gene's LOEUF score, 0.37, which puts it in group 1 of 6, group 1 being the genes least tolerant of losing a copy. Missense variants: 1,349 observed, 1,832.8 expected, observed/expected ratio (o/e) 0.74, 90% interval 0.7 to 0.77. Synonymous variants: 565 observed, 638.25 expected, observed/expected ratio (o/e) 0.89, 90% interval 0.82 to 0.95.
Homologues: Orthologues: chimpanzee ARHGEF12 (99% identical), macaque ARHGEF12 (99% identical), pig ARHGEF12 (93% identical), dog ARHGEF12 (92% identical), rabbit ARHGEF12 (92% identical), mouse Arhgef12 (89% identical), rat Arhgef12 (88% identical), guinea pig ARHGEF12 (86% identical), tropical clawed frog arhgef12 (58% identical), zebrafish arhgef12b (46% identical), zebrafish arhgef12a (45% identical), Drosophila melanogaster cyst (13% identical), and 1 more. Paralogues in human: ARHGEF11 (31% identical), ARHGEF1 (23% identical), ARHGEF28 (17% identical), ARHGEF18 (13% identical), ARHGEF2 (11% identical), PLEKHG6 (8% identical), NET1 (8% identical), ARHGEF3 (7% identical).
Diseases named in the same sentence as ARHGEF12 in open-access papers:
ARHGEF12 is named in the same sentence as 49 diseases in open-access papers, as found by Europe PMC text mining. Sharing a sentence is not in itself a finding about the gene and the disease. The quoted sentences say what the papers report.
leukemia (7 papers, 2006 to 2022). A malignant (clonal) hematologic disorder, involving hematopoietic stem cells and characterized by the presence of primitive or atypical myeloid or lymphoid cells in the bone marrow and the blood. "The most abundantly expressed RhoGEF in platelets is leukemia‐associated RhoGEF (LARG, also known as ARHGEF12) 6, a G protein–coupled receptor (GPCR)‐regulated GEF." (PMID 26334261, 2015).
acute myeloid leukemia (6 papers, 2013 to 2025). Acute myeloid leukemia (AML) is a group of neoplasms arising from precursor cells committed to the myeloid cell-line differentiation. "The leukemia-associated RhoGEF (LARG), also known as ARHGEF12, was initially identified as a novel fusion partner of the mixed-lineage leukemia protein in a patient with acute myeloid leukemia." (PMID 41338458, 2025). "Leukemia-associated RhoGEF (LARG/ARHGEF12), a member of the guanine nucleotide exchange factor family, was first identified in acute myeloid leukemia as a fusion partner of mixed-lineage leukemia." (PMID 41310897, 2025). "ARHGEF12 mutations were initially identified in acute myeloid leukemia and B-cell lymphoma, KMT2A-ARHGEF12 fusion caused hematologic disorders and associated with poor prognosis 22-24." (PMID 40860157, 2025).
breast carcinoma (4 papers, 2016 to 2021). "In all breast cancer cell lines examined, ArhGEF12 was found to be the primary RGS-RhoGEF for transmitting serum signaling." (PMID 33504879, 2021).
glioblastoma (4 papers, 2021 to 2025). The most malignant astrocytic tumor (WHO grade IV). "RSK2 phosphorylates leukemia-associated Rho GEF (LARG/ARHGEF12), a GEF for Rho, which is required for cell migration and invasion in glioblastoma cells." (PMID 38426123, 2024).
ovarian carcinoma (2 papers, 2023 to 2025). A malignant neoplasm originating from the surface ovarian epithelium. "As we know, we are the first to identify recurrent mutations of ARHGEF12 in GC with OM and demonstrate that ARHGEF12 mutations are recurrent in both GC and ovarian cancer patients." (PMID 40860157, 2025). "Given the relatively high recurrence rate of ARHGEF12 mutations in GC and ovarian cancer, and its enrichment in signaling pathways related to GC with OM, we further investigated the functions of ARHGEF12 mutations in GC." (PMID 40860157, 2025).
acute lymphoblastic leukemia (1 paper, 2023). Leukemia with an acute onset, characterized by the presence of lymphoblasts in the bone marrow and the peripheral blood. "Moreover, it was found that ARHGEF12 regulates cell adhesion and structure morphogenesis in esophageal squamous cell carcinoma tissues and plays a key role in erythroid regeneration after chemotherapy in acute lymphoblastic leukemia patients." (PMID 37228491, 2023).
bladder cancer (1 paper, 2025). "To elucidate the role of ARHGEF12 in bladder cancer initiation and progression, we performed scRNA-seq to map BLCA gene expression profiles at single-cell resolution." (PMID 41310897, 2025). "Our study indicates that ARHGEF12 promotes chemoresistance in bladder cancer cells by modulating RhoA/ROCK signaling, which subsequently activates the PI3K/AKT pathway." (PMID 41310897, 2025). "Collectively, these findings indicate that ARHGEF12 regulates cisplatin resistance in bladder cancer cells and underscore the precision of combining MR analysis with single-cell approaches to pinpoint candidate therapeutic targets." (PMID 41310897, 2025).
colon cancer (1 paper, 2023). "We speculate that CUR may block the binding of ARHGEF12-RhoA complex to suppress colon cancer cells, providing a new therapeutic strategy for colon cancer treatment." (PMID 37731740, 2023). "In summary, both TSGs ARHGEF12 and APAF1 expression were downregulated in colon cancer and could be reactivated by CUR, and upregulated ARHGEF12 and APAF1 may be associated with favorable prognosis of patients." (PMID 37731740, 2023). "Among them, ARHGEF12 and APAF1 genes, which were most significantly upregulated by CUR, were preferentially selected as candidate targets for CUR in colon cancer cells." (PMID 37731740, 2023). "ARHGEF12 is a newly identified TSG and a potential therapeutic target for colon cancer." (PMID 37731740, 2023). "This, for the first time, suggested that CUR might play a role in inhibiting tumor invasion and migration by blocking the binding of ARHGEF12 and RhoA, which provided a theoretical basis for the CUR treatment of colon cancer." (PMID 37731740, 2023). "Since ARHGEF12 has not been reported as a therapeutic target for colon cancer, we aimed to investigate the molecular mechanism by which CUR inhibits colon cancer by acting on ARHGEF12." (PMID 37731740, 2023). "Furthermore, molecular docking was performed to predict the binding sites of CUR and ARHGEF12, suggesting that CUR can prevent colon cancer cell invasion and metastasis by inhibiting ARHGEF12 and RhoA binding." (PMID 37731740, 2023). "Furthermore, we predicted the binding site of ARHGEF12 and found that CUR might inhibit the invasion and migration of colon cancer cells by inhibiting the binding of ARHGEF12 to RhoA." (PMID 37731740, 2023). "Considering that CUR can significantly reactivate TSGs ARHGEF12 and APAF1, to further investigate whether upregulated ARHGEF12 and APAF1 expression in colon cancer correlates with patient prognosis, we analyzed colon cancer subtypes using Kaplan-Meier survival curves." (PMID 37731740, 2023). "Therefore, we hypothesized that CUR reactivated the ARHGEF12 TSG to block colon cancer cell proliferation and migration via cancer pathways, whereas CUR might exert an inhibitory effect on invasion and migration by blocking the binding of ARHGEF12 to RhoA." (PMID 37731740, 2023).
coronary artery disease (1 paper, 2022). "These genes included Cdh13 and Lpl from Cluster 1; Nfia, Col4a1 and Serpinh1 from Cluster 2; Arhgef12, Col4a2, Scarb1 and Cst3 from Cluster 3; Pecam1 and Aldh2 from Cluster 4, providing plausible molecular basis for the inextricable causal link between age and coronary artery disease." (PMID 35615560, 2022).
COVID-19 (1 paper, 2022). A disease caused by infection with severe acute respiratory syndrome coronavirus 2. "On the other hand, 450 (22.96%) and 63 (41.18%) DEGs were downregulated (Down) in COVID-19 patients and recovered subjects, respectively, and of them, only 12 genes (i.e., MAFF, ARHGEF12, DCUN1D3, DR1, MT-CO1)." (PMID 36059456, 2022).
dementia (1 paper, 2025). Loss of intellectual abilities interfering with an individual's social and occupational functions. "Furthermore, elevated levels of Rho guanine nucleotide exchange factor 12 (ARHGEF12) was specifically linked to an increased risk of dementia." (PMID 41169480, 2025).
gastric adenocarcinoma (1 paper, 2022). "ARHGEF12 is a component of the E-cadherin adhesome defined by proximity proteomics in human gastric adenocarcinoma cells, an epithelial cell model." (PMID 35675330, 2022).
gastric cancer (1 paper, 2025). A primary or metastatic malignant neoplasm involving the stomach. "Subsequently, we analyzed ARHGEF12 mutation frequency across multiple cancer types in the Cosmic dataset and found that gastric cancer exhibited the second highest ARHGEF12 mutation frequency (6.16%, 100 out of 1623) among various cancer types." (PMID 40860157, 2025).
lichen planus (1 paper, 2025). A chronic, recurrent, pruritic inflammatory disorder of unknown etiology that affects the skin and mucus membranes. "Immunohistochemical results revealed that ARHGEF12 was highly expressed in MF tissue samples compared with lichen planus tissues." (PMID 40332203, 2025).
lung carcinoma (1 paper, 2015). "However, many “hits” in this study with no readily apparent representation in the lung cancer methylome-related literature were found, [e.g., PR: DARS, CLDN18, APIP; GB: ARHGEF12 PRKCE], and are likely worthy of pursuit." (PMID 26683690, 2015).
metastatic prostate carcinoma (1 paper, 2025). A carcinoma that arises from the prostate gland and has spread to other anatomic sites. "The fusion of ARHGEF12 with histone-lysine N-methyltransferase 2A gene (KMT2A) has been reported in leukemic patients 22, 23, and ARHGEF12 mutations have also been found in metastatic prostate cancer." (PMID 40860157, 2025).
psoriasis (1 paper, 2022). An autoimmune condition characterized by red, well-delineated plaques with silvery scales that are usually on the extensor surfaces and scalp. "In addition to the cytokines noted above such as IL17F (0.967), and CXCL13 (0.325), this set contained identified psoriasis-specific genes with less established functional roles, such as ARHGEF12 (0.303), ENTPD1 (0.628), LAYN (0.122) and HAVCR2 (0.560)." (PMID 35958578, 2022).
pulmonary arterial hypertension (1 paper, 2025). Pulmonary arterial hypertension (PAH) is a group of diseases characterized by mean pulmonary artery pressure >20 mmHg and elevated pulmonary arterial resistance leading to right heart failure. "ARHGEF12, also known as leukemia-associated Rho GEF (LARG), has been implicated in the progression of various diseases, including cancer, pulmonary arterial hypertension, and pathogenic thrombus formation, primarily through its role in RhoA activation and its effects on the actin cytoskeleton." (PMID 41306285, 2025).
retinal disease (1 paper, 2022). "The identification of Arhgef12 and Prkci as Crb1 modifier genes in mice may have relevance to diagnosing and developing treatments for human CRB1-associated retinal disease." (PMID 35675330, 2022).
Retinal dysplasia (1 paper, 2022). Abnormal growth and differentiation, structure and appearance of the retina present from birth. "Accordingly, the loss of ARHGEF12 in Tvrm266 mice would abolish this response and exacerbate retinal dysplasia." (PMID 35675330, 2022). "Epistatic analysis revealed a genetic interaction between Arhgef12 and Crb1 alleles that led to enhanced retinal dysplasia, suggesting that both genes participate in the same pathogenic pathway." (PMID 35675330, 2022).
Retinal dystrophy (1 paper, 2022). Retinal dystrophy is an abnormality of the retina associated with a hereditary process. "Our finding that mutations in murine Arhgef12 and Prkci modulate Crb1rd8 retinal phenotypes to differing extents and with different lesion characteristics further supports the hypothesis that modifier gene variants contribute to clinical variability in CRB1-associated retinal dystrophy." (PMID 35675330, 2022).
cancer (21 papers, 2008 to 2025). A tumor composed of atypical neoplastic, often pleomorphic cells that invade other tissues. "Although ARHGEF12 mutations have been found in several cancers 22, 23, 71, the functions of these mutations remain largely unclear." (PMID 40860157, 2025). "Based on the reported researches, ARHGEF12 binds to RhoA to shape a functional complex, thereby enhancing cancer cell migration and invasion." (PMID 37731740, 2023). "ARHGEF12, also known as leukemia-associated Rho guanine-nucleotide exchange factor (LARG), is underexpressed in CRC tissue and is associated with reduced cell proliferation and a slower migration rate in cancer cells." (PMID 37228491, 2023). "These genes related to ARHGEF12 all play crucial roles in the Rho signaling pathway, and their functions in cancer initiation, proliferation, metastasis, and drug resistance are well supported by previous research." (PMID 33573703, 2021). "Notable alterations in human cancer gene orthologs impacted by SVs in single cases include an ARHGEF12 inversion, a BIRC3 inversion, a CLPTM1L-TERT translocation, a DDIT3 inversion, a MYO5A translocation, and a TCF12 inversion." (PMID 30188888, 2018). "To date, the role of ARHGEF12 in cisplatin chemoresistance remains unexplored in cancer therapy." (PMID 41310897, 2025). "Hence, the strong TS genes SASH1, STARD13, RECK, CBFA2T3, RASSF2, RAP1A, and ARHGEF12 can be used as specific biomarkers for diagnosis of NSCLC cancer." (PMID 33580150, 2021). "The Cancer Genome Atlas (TCGA) data analysis indicated that the gene expression of TRIO, NET1, ECT2, TIAM2, FARP1, ARHGEF12 and BCR in primary cancer was significantly higher than those in normal tissues." (PMID 32029704, 2020). "HeLa cell lysate was also used in the other western blots, with expression of ARHGEF1, ARHGEF11, ARHGEF12, ARHGAP5, ARHGAP24 and ARHGDIA protein reported in this cancer cell line." (PMID 18190708, 2008).
tumor (16 papers, 2012 to 2025). "Subsequent in-depth functional assays revealed that the E620K mutation of ARHGEF12 as a gain-function mutation promotes OM of GC through tumor-derived ITGA6-high exosomes." (PMID 40860157, 2025). "Mechanistically, the downregulation of METTL3-mediated m6A modification on ARHGEF12 mRNA accelerated its degradation, a process that is closely associated with tumor behaviors." (PMID 40332203, 2025). "We also demonstrate that ARHGEF12 mutation may contribute to OM of GC via tumor-derived exosomes containing specific integrins." (PMID 40860157, 2025). "Consistently, CAFs educated by exosomes from ARHGEF12-transduced MFC cells significantly promoted tumor growth compared with those educated by exosomes from EV-transduced MFC cells." (PMID 40860157, 2025). "Mechanistically, ARHGEF12 E620K mutation upregulated ITGA6 expression through Rap1 signaling pathway activation and promoted tumor-derived ITGA6-high exosome formation, which were preferentially uptaken by ovarian fibroblasts." (PMID 40860157, 2025). "The results implicate ARHGEF12 in regulation of the PI3K–Akt signaling pathway in BLCA, whose aberrant activation is closely linked to tumor progression." (PMID 41310897, 2025). "ARHGEF12 was recurrently inserted by HBV in tumor-adjacent tissues of HBV-related HCC samples to increased its gene expression." (PMID 34357116, 2021). "For instance, ARHGEF12 is a well-studied activator of Rho signaling downstream of G-protein-coupled receptors (GPCRs) and has essential roles in chemokine-driven tumor cell invasion." (PMID 33573703, 2021). "We found that mRNA and protein levels of ARHGEF12 were highly expressed in tumor cells." (PMID 40332203, 2025). "ARHGEF12 depletion reduced tumor growth, whereas overexpression of ARHGEF12 promoted OM of GC." (PMID 40860157, 2025). "ARHGEF12 has previously been reported as a proto-oncogene in several tumor types." (PMID 40332203, 2025). "In addition, we also found that HBV integration to the ARHGEF12 gene in the tumor-adjacent tissues increased their expression." (PMID 23236287, 2012). "Importantly, we found novel protein changes including high levels of oncogenic proteins such as R-Spondin 3 (RSPO3) and secernin 1 (SCRN1) as well as low levels of tumor suppressors such as Ret proto-oncogene (RET) and Rho guanine nucleotide exchange factor 12 (ARHGEF12) in CRC patients." (PMID 37228491, 2023).
infection (2 papers, 2023). The state of being infected such as from the introduction of a foreign agent such as serum, vaccine, antigenic substance or organism. "The topological plots showed that GNA13 and ARHGEF12 were significantly downregulated at 48 h post-infection, and these genes inhibit the Calcium signaling pathway by regulating ROCK1 and MYL12A." (PMID 37211158, 2023).
cardiovascular diseases (1 paper, 2025). "The mechanistic overlap between cardiovascular diseases and cancer (e.g., shared roles of ARHGEF12, CTNNB1, and PTEN) may inform dual therapeutic strategies." (PMID 41020039, 2025).
ARHGEF12 also shares sentences with these, for which no sentence is quoted: Hypertension (3 papers); Sepsis (3); diabetes (2); T-Cell Lymphoma (2); acute leukemia (1); B-cell lymphoma (1); colorectal cancer (1); diffuse large B-cell lymphoma (1); esophageal squamous cell carcinoma (1); exfoliation syndrome (1); glioma (1); hematologic disorder (1); hypospadias (1); leishmaniasis (1); Neonatal sepsis (1); neuroblastoma (1); Obesity (1); osteosarcoma (1); parasitemia (1); peripheral T cell lymphoma (1); prostate carcinoma (1); prostate tumors (1); thyroid cancer (1); viral infection (1).